GDF15 (growth differentiation factor 15)
Diseases named in the same sentence as GDF15 in open-access papers (continued):
Sharing a sentence is not in itself a finding about the gene and the disease.
infection (57 papers, 2011 to 2026). The state of being infected such as from the introduction of a foreign agent such as serum, vaccine, antigenic substance or organism. "In contrast to the beneficial effect of GDF15, it has been reported that GDF15 deficiency limits neutrophil recruitment to the site of infection and delays local pathogen control and clearance in bacterial infection." (PMID 38725041, 2024). "They reported that GDF-15 was associated with the pathogenesis of hepatitis C virus as a host response to viral proteins, infection-induced cell stress or both." (PMID 34777864, 2021). "Whether the observed infection-mediated appetite suppression is directly linked to elevated rainbow trout GDF-15 and/or leptin levels in this model requires further study." (PMID 37928534, 2023). "An elevated serum GDF-15 level was associated with infection and inflammation, metabolism indicators, and the disease severity of IPF and could predict AE occurrence and the survival in IPF subjects." (PMID 35784345, 2022). "Though the underlying infection may be a simple explanation, enhanced ferroportin-mediated iron efflux due to overexpression of growth differentiation factor 15 may play a role." (PMID 34340686, 2021). "Most recently, GDF15 has been recognized to be an inflammation-related hormone that is essential for surviving infections." (PMID 38725041, 2024). "Promotion of catabolism indeed appears to represent a primary function and correlate of GDF15 in many contexts, including infection, injury, frailty and aging." (PMID 38711789, 2024). "It is of particular importance concerning GDF-15, the functions of which were recently summarized as “stress-, infection-, and inflammation-induced cytokine, which expression is increased in aging and suppresses immune responses”." (PMID 38255954, 2024). "Recent work has demonstrated that GDF15 is both sufficient to increase corticosterone and necessary for increases in corticosterone induced by infection or chemical toxins in mice." (PMID 39480267, 2024). "In particular, the prognostic role of GDF-15 was more reliable in the early phase of the infection, when compared with other inflammatory biomarkers, including CRP, ferritin, D-dimer, and IL-6." (PMID 38700782, 2024). "CXCL10/IP-10 was significantly elevated at all times of infection, and GDF-15/MIC-1 had considerably higher levels in all patients with COVID-19." (PMID 36851766, 2023). "To further delineate the effect of CS on RV-A16 infection, we performed growth differentiation factor 15 (GDF15) knockdown, l-lactate and interferon pre-treatment in ALI-PBEC." (PMID 37612597, 2023). "In the combined analysis, variables significantly associated with infection were elevated STNC, GDF-15, Cath2, Hapt, Lept, and C1q-LP3 and decreased PCV." (PMID 37928534, 2023). "In mammals, elevated plasma levels of GDF-15 or leptin have independent roles in appetite suppression and energy homeostasis and can modulate host response to pathogen infection." (PMID 37928534, 2023). "On the other hand, GDF-15 knockout mice were shown to be protected against severe septic infection, with prolonged survival, and demonstrated better control over local infections." (PMID 35251002, 2022). "Two cytokines directly related to signs of infection or injury and loss of muscle mass are, respectively, C-reactive protein (CRP) and growth differentiation factor-15 (GDF-15)." (PMID 36499366, 2022). "These markers returned to levels comparable to controls after one week, except PTX-3 that remained elevated in patients with Delta infection after one week, and GDF-15 that remained elevated in both groups." (PMID 36159859, 2022). "After 72 h of infection, the myotubes with GDF-15 overexpression were significantly thinner than those infected by vector virus." (PMID 35379793, 2022).
infection (continued). "In our cohort study of IPF patients, GDF-15 serum levels correlated positively with the clinical variables of infection and inflammation and negatively correlated with several metabolic indicators." (PMID 35784345, 2022). "RAW264.7 cells were infected with MNV at different MOIs for 24 h, equivalent to 2 rounds of infection (12 h p.i.)and treated with 0.125 μg/ml to 1 μg/ml of GDF15-neutralizing antibody before assessing cell survival." (PMID 34346771, 2021). "Consistent with a largely GDF15-independent effect of infection on the HPA axis, in human participants injected with low-dose endotoxin the acute rise in cortisol as well as inflammatory factors preceded the rise in GDF15." (PMID 34187898, 2021). "Studies in mice suffering from polymicrobial infection including P. gingivalis revealed increased expression of Gdf15 in PdL tissue." (PMID 34948405, 2021). "All tested cytokines had lower levels in Gdf15−/− mice, which reached statistical significance in the cases of IL-1β and IL-12 suggesting better control of infection in Gdf15−/− mice." (PMID 32424099, 2020). "Whatever the true biological role of GDF15 in infection, it is clear that its conclusive elucidation is critical as the modulation of GDF15 is rapidly being tested in clinical trials for different conditions." (PMID 32424099, 2020). "In the present study, we used a model of peritoneal sepsis; further work is needed to test the significance of GDF15 regulation on CXCL5-mediated neutrophil recruitments for other origins of infection, including lung bacteria pneumonia." (PMID 32424099, 2020). "Since GDF15 plays a role in infection, we assessed the occurrence of cytomegalovirus (CMV) and BKPyV DNAemia in our cohort." (PMID 32375259, 2020). "For example, the transcripts encoding Gdf15, a TGF-β superfamily cytokine, and Vegfa, an angiogenic endothelial cell growth factor, were dramatically stabilized and up-regulated following infection with reovirus isolates c8 and c87." (PMID 30261045, 2018). "During infection, liver Hamp expression levels remain suppressed and Gdf15, Il1 and Il6 expression increased significantly in Ank1Ity16/Ity16 mutant mice compared to wild type littermates." (PMID 23390527, 2013). "During infection, the levels of Gdf15 were significantly more elevated in Ank1Ity16/ity16 mutant mice compared to wild type littermates." (PMID 23390527, 2013). "Among other genes found to display high, and significant expressional levels during infection were IL-1α, IL-32, growth differentiation factor 15 (GDF15) and, chemokine (C-C motif) ligand 22 (CCL22)." (PMID 23646188, 2013). "Additionally, diverse pathologies associated with neurodegenerative diseases, infection, ischemia, and traumatic injury are linked to increased levels of OSM, LIF, GDF-15, and FGF-2." (PMID 39683685, 2024). "The actions of GDF15 are adaptive in the face of tissue damage or infection/illness." (PMID 39737892, 2024). "GDF15 regulates a variety of functions, including food intake (via appetite and nausea induction), expenditure of energy, and bodily responses to stresses including infection and injury." (PMID 38711789, 2024). "Hence, ELISA showed elevation of plasma GDF-15 levels during the acute phase of the infection, which lasted for at least 30 days, and decreased to levels observed in health controls after months of recovery." (PMID 38686386, 2024). "In addition to a metabolic function, GDF-15 recently emerged as an inflammation-induced mediator of disease tolerance through cellular metabolic reprogramming in the context of infections." (PMID 35251002, 2022). "Finally, GDF-15 has been shown to be released due to infection with a variety of bacterial and viral pathogens, and that it plays a tissue protective role during infection via regulation of lipid metabolism." (PMID 35821815, 2022). "In terms of infections, a protective role was attributed to GDF15." (PMID 32375259, 2020).
infection (continued). "Higher upon-admission serum GDF15 concentrations and randomization to early PN versus late PN were independently associated with a lower likelihood of early live ICU discharge and higher risks of acquiring a new infection or muscle weakness." (PMID 32928255, 2020). "Deficiency or knockdown of GDF15 in DCs increased the expression of MHCII, CD40,CD80 CD83, and CD86, while over expression of GDF15 either by using GDF15 TG DCs or infection with GDF15-Ad reduced the expression of these molecules, in comparison with WT untreated DCs." (PMID 30425709, 2018). "Both FGF21 and GDF15 are critical in host defense by promoting tolerance: in models of bacterial sepsis they induce thermoregulation, and triglyceride release respectively and thus protect the heart by regulating the increased cardiac metabolic demands of infection." (PMID 34777390, 2021). "Furthermore, they stated that the increase in GDF-15 is caused by fibrosis rather than the hepatocellular damage by the infections in chronic liver diseases." (PMID 34777864, 2021). "Indeed, the levels of corticosterone reached with these powerful infection-related stimuli may be close to maximal, thereby obscuring any effects of GDF15." (PMID 34187898, 2021). "Hepcidin synthesis is enhanced by high iron levels, infection, and inflammation, but inhibited by erythropoiesis in the bone marrow via ERFE and growth differentiation factor-15 (GDF-15)." (PMID 39940645, 2025). "The role of GDF-15 is still unclear, but GDF-15 seems to be produced, among others, during infections, tissue damage and acts as a metabolic and energy regulator." (PMID 38700782, 2024). "On the other hand, overexpression of YB-1 in CMs, caused by infection with an adenovirus encoding YB-1 (AdYB-1), prevented hypertrophic growth under α-adrenergic stimulation with phenylephrine (PE), but not under stimulation with growth differentiation factor 15 (GDF15; n = 10–16)." (PMID 38203580, 2023). "We demonstrated that CS increased both RV-A16 vRNA and GDF15 levels at 24hpi, and that IFN-λ1 levels were similar upon RVA-16 infection in both air and CS-exposed cells." (PMID 37612597, 2023). "Growth differentiation factor-15 (GDF-15) is a stress-, infection-, and inflammation-induced cytokine which is increased in aging and suppresses immune responses." (PMID 35821815, 2022). "The transcripts of TNF and RANKL (the TNF family) and of GDF15 and INHBA (the TGF-ß family) were also induced in mice and monkeys upon infection by C. neoformans." (PMID 31329596, 2019). "The mean serum levels of GDF-15 (pg/ml) were significantly higher in patients who developed infectious complications compared with those without infections (959.5 ± 273.1 vs. 742.8 ± 377.5; p = 0.008)." (PMID 38700782, 2024). "Endogenous GDF15 was not required for the HPA response to infection-related stimuli but was essential for the response to the administration of toxins of two different classes." (PMID 34187898, 2021). "We undertook a set of experiments to examine whether GDF15 might be involved in the HPA response to stress; possibly synergizing with cytokines in the case of infections and/or playing a more prominent role in the response to chemical stressors." (PMID 34187898, 2021). "Lentiviral infection system was used to knockdown GDF-15 expression, the results indicate that cell proliferation was decreased significantly after knocking down GDF-15 expression in AsPC-1 and BxPC-3." (PMID 33201838, 2020). "Taken together, the results for cytokines, serologic markers of organ lesion, histopathology, and bacterial burden suggest that Gdf15−/− mice are more resistant to infection without affecting disease tolerance." (PMID 32424099, 2020). "This has resulted in significant progress over the last 4 years in the understanding of the previously little known secretory factors such as neurotensin (NT), growth differentiation factor-15 (GDF-15), sphingosine-1-phosphate S1P, and of infection with cytomegalovirus (CMV)." (PMID 29467963, 2018).
infection (continued). "However, there were significant differences in GDF-15 serum levels, WBC counts, triglyceride (TG), total cholesterol (TCHL), low cholesterol (LCHL), and glucose (GLU), which are related to infection and metabolism (p < 0.001, p < 0.001, p = 0.003, p = 0.014, p = 0.022, and p < 0.001, respectively)." (PMID 35784345, 2022). "Moreover, to our knowledge, no study has yet investigated the role of GDF15 in the enhanced inflammatory response of force-stimulated HPdLF that typically occurs with concurrent P. gingivalis-LPS infection." (PMID 34948405, 2021). "Thus, although GDF15 levels increased markedly in response to infection-related stimuli, this was not necessary for the activation of the HPA axis." (PMID 34187898, 2021). "We then measured the bacterial load in the peripheral blood of WT and Gdf15−/− mice in independent experiments and found consistently a statistically significant lower bacterial burden in Gdf15−/− mice at 8 h after CLP, suggesting that better control of the initial local infection in Gdf15−/− mice." (PMID 32424099, 2020). "We still do not understand how GDF15 negatively regulates CXCL5-mediated neutrophil recruitment to the site of infection, but previous reports have shown that GDF15 regulates neutrophil arrest and platelet aggregation under flow conditions by modulating the affinity of integrins." (PMID 32424099, 2020).
heart disease (37 papers, 2013 to 2026). "The aim of this study was to determine if there is an association between plasma GDF15 levels, heart disease and mortality in a representative population-based cohort." (PMID 41977265, 2026). "In 940 71-year-old subjects followed for 10 years, an increase in GDF-15 levels was associated with a stronger risk of cardiovascular mortality, total mortality and coronary-heart-disease-related morbidity and mortality." (PMID 31258506, 2019). "Nevertheless, our current results clearly demonstrate that heart‐derived GDF15 is essential for altered liver GH signaling in FTT associated with pediatric heart disease." (PMID 28572090, 2017). "While its relevance in cardiac disease has been extensively examined, GDF15 remains underexplored in the context of PAD." (PMID 40806859, 2025). "Proteins such as CDCP1, CXCL17, FGF21, GDF15, and IGFBP4 commonly mediated effects in both the Air and Noise Pollution and Social Deprivation groups, while GDF15 was notably linked to heart disease across these patterns." (PMID 41290610, 2025). "For GDF-15, on the other hand, its absence in fibrotic myocardium suggests other sources of circulating GDF-15 in heart disease." (PMID 38739599, 2024). "Both in our hands and others, Gdf15 levels rise concurrently with the onset and severity of cardiac disease in murine FA models." (PMID 37260376, 2023). "GDF-15 is not only important in heart disease but also serves as an inflammatory marker in other ailments such as cancers, neurodegenerative and ischemic diseases." (PMID 37484982, 2023). "In accordance with the GDF-15 results, it appears pericardial fluid is more accurate than serum in predicting cardiac diseases." (PMID 34441356, 2021). "Our cardiac‐specific Gdf15 knockdown studies suggest that cardiac‐derived GDF15 in the heart disease condition contributed to all the elevated circulating GDF15 above basal level." (PMID 28572090, 2017). "We measured plasma GDF15 concentrations in children diagnosed with heart disease and with either normal body weight or FTT." (PMID 28572090, 2017). "Both groups of children with heart disease had significantly higher plasma GDF15 levels than gender‐ and age‐matched healthy control children, consistent with previous findings that plasma GDF15 was increased in adult heart disease." (PMID 28572090, 2017). "We show that GDF15 is both sufficient and required for inhibition of liver GH signaling in FTT associated with pediatric heart disease." (PMID 28572090, 2017). "Plasma GDF15 was found elevated in various heart diseases in many independent biomarker studies and in animal models." (PMID 28572090, 2017). "We observed a fourfold to fivefold increase of circulating GDF15 in αKOγKO mice and similar changes in children with heart disease." (PMID 28572090, 2017). "GDF-15 is a cardiac hormone predominantly induced by injury and may be a useful biomarker in the diagnosis of cardiac diseases." (PMID 37484982, 2023). "In fully-adjusted models, GDF15 predicted death from heart disease." (PMID 34445593, 2021). "GDF15 synthesis and secretion by cardiomyocytes are involved in the development of heart diseases." (PMID 34445593, 2021). "We show that pediatric heart disease induces GDF15 synthesis and secretion by cardiomyocytes." (PMID 28572090, 2017). "However, the exact organ source and biological function of increased circulating GDF15 in heart disease remain little understood." (PMID 28572090, 2017). "However, the organ source and biological function of increased circulating GDF15 in heart disease are little known." (PMID 28572090, 2017). "GDF15 synthesis and secretion by cardiomyocytes are increased in pediatric heart disease." (PMID 28572090, 2017). "Plasma GDF15 level was reported to be elevated in many forms of adult heart disease in both patients and animal models and was therefore recently proposed as an independent biomarker for heart diseases." (PMID 28572090, 2017).